TNF (tumor necrosis factor)
Diseases named in the same sentence as TNF in open-access papers (continued):
Sharing a sentence is not in itself a finding about the gene and the disease.
Tinnitus (38 papers, 2011 to 2025). Tinnitus is an auditory perception that can be described as the experience of sound, in the ear or in the head, in the absence of external acoustic stimulation. "The important role of TNF in tinnitus associated with inflammatory processes involving most of the HSIPs has recently been reviewed." (PMID 40565265, 2025). "Inflammatory markers like TNF-α have been linked to tinnitus, thereby underlining the necessity for innovative therapies." (PMID 38398306, 2024). "Anti-TNF-α therapy, such as Etanercept, was studied to prevent noise-induced hearing loss, and was recently studied in tinnitus as well." (PMID 38327985, 2024). "They observed that there were elevated levels of pro-inflammatory cytokines/ interleukins, such as IL-1 β, IL-18, TNF-α, and that noise-induced neuroinflammatory response resulted in excitatory-to-inhibitory synaptic balance and caused tinnitus." (PMID 37305742, 2023). "The tinnitus scores of salicylate-treated mice showed significant positive associations with the expression levels of the TNF-a and IL-1b, and NR2B genes." (PMID 38027533, 2023). "In TNF knockout mice or during blockade of TNF expression pharmacologically, neuroinflammation is reduced and the behavioural phenotype associated with tinnitus in animals is improved." (PMID 37373034, 2023). "Following tinnitus and hearing loss driven by noise exposure, greater microglial reactivity in terms of morphological changes and inflammatory cytokine levels (such as TNF-α and IL-1β) were observed in the central auditory system of mice." (PMID 37600010, 2023). "Further, in mice, intra-ventricle infusion of recombinant TNFα resulted in tinnitus behavior and microglia alterations in the AC following noise exposure, and genetic knockout of TNFα or blockade of TNFα expression decreased tinnitus-associated behavior." (PMID 36902722, 2023). "There is accumulating evidence that tinnitus is associated with neuroinflammation, such as a positive correlation between the circulating cytokines IL-1β and TNF-α with psychometric scores of tinnitus." (PMID 37048724, 2023). "Certain polymorphisms in the TNF gene are associated with susceptibility to tinnitus among older individuals with occupational noise exposure." (PMID 36902722, 2023). "In the present study, the gene sets associated with diuretics, fenofibrate, tumor necrosis factor-alpha inhibitor, and metformin showed significant enrichment with tinnitus." (PMID 36581688, 2022). "Taken altogether, it is probable that noise exposure and salicylate administration cause an increase in TNF-α, which leads to acute tinnitus." (PMID 35207270, 2022). "In total, five pathways showed significant associations with noise-induced tinnitus, including the arachidonic acid metabolism, inositol phosphate metabolism, Notch signaling, Wnt signaling and tumor necrosis factor (TNF) pathways (all P < 0.05)." (PMID 34482816, 2021). "In humans, polymorphisms of several inflammatory cytokines, including TNF-α, are associated with the risk of noise-related tinnitus, a central auditory disorder that is often comorbid with impairment in gap detection." (PMID 33154715, 2020). "This interpretation is consistent with findings that polymorphisms of inflammatory cytokines, including TNF-α, are associated with the risk of tinnitus, especially in those with a history of occupational noise exposure." (PMID 33235216, 2020). "Tumor necrosis factor alpha (TNF-α) expression is elevated by loud noise exposure in the auditory periphery and cochlear nucleus and is implicated in tinnitus." (PMID 31211773, 2019). "The tinnitus scores of salicylate-treated mice showed significant positive associations with the expression levels of the TNF-α and IL-1β, and NR2B genes." (PMID 21477330, 2011). "Linear regression analysis revealed a significant positive association between tinnitus scores and expression levels of TNF-α, IL-1β, and NR2B genes in cochlea and IC." (PMID 21477330, 2011).
Tinnitus (continued). "Additionally, inhibiting or genetically mutating tumor necrosis factor alpha (TNF-α) has been shown to alleviate behavioral symptoms associated with tinnitus in animal models." (PMID 39555931, 2025). "TNFα has been implicated in some exploratory human studies of tinnitus." (PMID 36902722, 2023). "Finally, TNF-α and IL-1β gene expression in the IC and cochlea were both positively associated with tinnitus scores after four days of salicylate injections." (PMID 35207270, 2022). "As a result of conducting a progressive muscle relaxation (PMR) program and regular training at home through psychiatrists for patients with tinnitus, stress perception, anxiety, and discomfort caused by tinnitus, as well as TNF-α, a pro-inflammatory cytokine, were decreased." (PMID 34205595, 2021). "As for the TNF pathway, genetic knockout of tumor necrosis factor-alpha (TNF-α) or pharmacologically blocking TNF-α expression ameliorated the behavioral phenotype associated with noise-induced tinnitus in mice." (PMID 34482816, 2021). "Genetic knockout and pharmacological blockade of TNFα, a proinflammatory cytokine also involved in regulating homeostatic plasticity, prevented noise-induced generation of tinnitus; conversely, TNFα administration caused tinnitus behavior in normal-hearing animals." (PMID 32591097, 2020). "Using genetic knockout and pharmacologic blockade of TNF-α, the authors conclude that targeting neuroinflammation may be a therapeutic strategy for tinnitus and other hearing loss-related disorders." (PMID 31632328, 2019). "In addition, the tinnitus scores showed significant positive associations with the gene expression levels of TNF-α, IL-1β, and NR2B in both cochlea and IC." (PMID 21477330, 2011). "Animal studies often measure TNF-α immediately after tinnitus induction, while clinical studies assess cytokines in chronic tinnitus patients, potentially after TNF-α levels have normalized." (PMID 40697272, 2025). "Inflammatory markers such as TNF-α and IL-1β were found to be increased in tinnitus, and inflammatory cells such as microglia and astrocytes were found to be activated." (PMID 38719997, 2024). "After matching, 2.1% (n = 50) of the TNFα-FP cohort and 1.5% (n = 146) of the TNFα-AB cohort were diagnosed with tinnitus during the study period; the mean time to tinnitus diagnosis from index was 1135.4 (SD: 838.5) and 1063.1 (900.5) days, respectively." (PMID 36902722, 2023). "TNFα expression is also significantly upregulated in the IC or AC of mice with salicylate-induced tinnitus." (PMID 36902722, 2023). "Separate comparisons of tinnitus incidence were conducted between the TNFα-FP (n = 3506) and TNFα-AB (n = 10,859) cohorts and a random sample of 25,000 patients who did not receive anti-TNFα therapy." (PMID 36902722, 2023). "In animal models, noise exposure prompted an inflammatory response along the central auditory pathway, resulting in behavior consistent with tinnitus and increased expression of proinflammatory cytokines, particularly tumor necrosis factor-alpha (TNFα)." (PMID 36902722, 2023). "Further, treatment with 3,6′-dithiothalidomide (TNF-α inhibitor), to prevent microglial reactivity, also led to reduced tinnitus." (PMID 37600010, 2023). "Recent studies have shown that the gut microbiome plays a role in regulating the concentration of neurotransmitters like GABA and serotonin, as well as inflammatory mediators like TNF-alpha and IL-6, potentially contributing to tinnitus." (PMID 37887847, 2023).
Tinnitus (continued). "Mice with tinnitus showed an increase in TNF-α gene expression in both auditory cortices twelve hours, one day and ten days after noise exposure, with a significantly higher expression in the ipsilateral AC than in the contralateral AC after twelve hours." (PMID 35207270, 2022). "The central role of microglia is further supported by the observation that microglial depletion prevented an increase in TNF-α expression and noise-induced tinnitus." (PMID 35207270, 2022). "So, besides increasing excitatory neurotransmission, TNF-α and IL-1β presumably also suppress inhibitory neurotransmission in tinnitus." (PMID 35207270, 2022). "It was established that TNF-α and IL-1β are increased in tinnitus, and that microglia and astrocytes are activated as well." (PMID 35207270, 2022). "TNF-α was consistently increased after tinnitus induction and infusion of TNF-α in the AC of healthy mice resulted in tinnitus." (PMID 35207270, 2022). "The first network included tinnitus loudness (SL) and correlated blood parameters (TNF-α, IL-1b, IGF-1) and their covariates (age, hearing threshold, systolic blood pressure, LDL cholesterol, VEGF, non-classical monocytes, intermediate monocytes)." (PMID 35814090, 2022). "Conversely, infusion of TNF-α into primary auditory cortex resulted in behavioral signs of tinnitus in wild-type and TNF-α knockout mice with normal hearing." (PMID 36401375, 2022). "In an exploratory study in 30 chronic tinnitus patients, a positive correlation between TNF-α and tinnitus loudness (determined by a visual analog scale) and a negative correlation with the subscale “joy” of the PSQ was observed." (PMID 35814090, 2022). "Intriguingly, the newly identified significantly associated genes WNT11 and TNFRSF1A were just in the Wnt and TNF pathways, respectively, therefore highlight the critical roles of these two pathways in the development of tinnitus." (PMID 34482816, 2021). "In the same study, blocking TNF-α expression also prevented behavioral evidence of tinnitus assessed with an operant perceptual task." (PMID 33154715, 2020). "To further investigate the role of neuroinflammation in tinnitus, we examined the effect of 3,6′-dithiothalidomide (dTT)—a TNF-α inhibitor that has been shown to reduce neuroinflammation—on noise-induced tinnitus." (PMID 31211773, 2019). "Genetic knockout of tumor necrosis factor alpha (TNF-α) or pharmacologically blocking TNF-α expression prevented neuroinflammation and ameliorated the behavioral phenotype associated with tinnitus in mice with NIHL." (PMID 31211773, 2019). "We found that blocking TNF-α expression by dTT significantly reduced behavioral evidence of tinnitus in the conditioning-based test, confirming that neuroinflammation contributes to tinnitus etiology." (PMID 31211773, 2019). "To determine the contribution of microglia to noise-induced TNF-α expression and tinnitus, we eliminated a proportion of microglia with PLX3397, an inhibitor of colony-stimulating factor 1 receptor (CSF1R)." (PMID 31211773, 2019). "Conversely, infusion of TNF-α into AI resulted in behavioral signs of tinnitus in both wild-type and TNF-α knockout mice with normal hearing." (PMID 31211773, 2019). "Together, these results suggest that the proinflammatory cytokine TNF-α is required for the noise-induced tinnitus that we observed 10 days after noise exposure." (PMID 31211773, 2019). "To examine a potential role of noise-induced neuroinflammation in tinnitus, we tested noise-induced tinnitus in TNF-α knockout mice using the acoustic startle reflex-based gap detection test." (PMID 31211773, 2019). "While unexpected in this model, increased TNFα following salicylate has been reported in models of tinnitus." (PMID 25874611, 2015). "Post-hoc analysis showed that, compared to the control group, the tinnitus group had significantly increased TNF-α mRNA levels in the cochlea (1.9±0.2 versus 0.9±0.1, p<0.001) and IC (2.1±0.2 versus 1.7±0.2, p<0.001)." (PMID 23533584, 2013).
Tinnitus (continued). "Salicylate-induced tinnitus was associated with up-expression of NR2B, TNF-α, and IL-1β genes and with enzymatic inhibition of COX." (PMID 23533584, 2013). "We evaluated tinnitus and mRNA expression levels of TNF-α, IL-1β, and N-methyl D-aspartate receptor subunit 2B (NR2B) genes in cochlea and inferior colliculus (IC) of mice after intraperitoneal injections of salicylate." (PMID 21477330, 2011). "Linear regression analysis showed that tinnitus scores were positively associated with gene expression level of NR2B and with gene expression levels of TNF-α and IL-1β in cochlea and IC." (PMID 21477330, 2011). "Activated platelets release cytokines like IL-6, IL-8, and TNF-α within minutes, potentially contributing to prothrombotic conditions or thrombotic events in the internal auditory artery, leading to cochlear hypoperfusion and tinnitus." (PMID 40697272, 2025). "There are several explanations for the lack of an association between use of anti-TNFα inhibitors and tinnitus in this study population despite promising results in animal models." (PMID 36902722, 2023). "Although some evidence suggests a link between TNFα and tinnitus genesis, it is unknown whether anti-TNFα therapy influences the development of tinnitus." (PMID 36902722, 2023). "Tinnitus is not a known adverse event associated with anti-TNFα therapy and is not reported as occurring in their pivotal clinical trials or in their FDA prescribing information." (PMID 36902722, 2023). "Tinnitus incidence was compared among patients with or without anti-TNFα therapy, overall and among at-risk age groups or by anti-TNFα category." (PMID 36902722, 2023). "Future well-controlled studies may determine whether the timing of tinnitus onset or the method of anti-TNFα delivery are key factors in the treatment effect." (PMID 36902722, 2023). "Additionally, infusion of TNF-α led to a tinnitus phenotype in mice, while knockdown or inhibition of TNF-α, as well as microglial depletion, prevented tinnitus." (PMID 37048724, 2023). "Therefore, elevated levels of TNF-α can (also) be attributed to the presence of tinnitus in animals." (PMID 35207270, 2022). "Given the role of TNF-α, IL-1β and microglia in the tinnitus pathophysiology, these mediators could potentially be a target for treatment." (PMID 35207270, 2022). "After infusion of TNF-α, these animals developed tinnitus as well." (PMID 35207270, 2022). "This is suggested by a study in which a reduction in TNF-α levels and a concomitant reduction in tinnitus disturbance, perceived stress levels, anxious depression, and anger symptoms were observed after a 10-week relaxation program in chronic tinnitus patients." (PMID 35814090, 2022). "Additionally, pharmacological depletion of microglia before noise exposure prevented a TNF-α increase and noise-induced tinnitus." (PMID 35207270, 2022). "Interestingly, this increase was consistently coexistent with increases in TNF-α and IL-1β in animals with tinnitus throughout the entire auditory pathway." (PMID 35207270, 2022). "Moreover, genetic deletion and pharmacological blockade of TNF-α prevented the occurrence of tinnitus and noise-induced microglial activation." (PMID 35207270, 2022). "Accordingly, the inhibition of TNF- in a genetic knockout or by a pharmacological inhibitor decreased the expression of the neuroinflammatory genes TNF-, IL1, IL18, and Nod-like receptor protein 3, and prevented microglial activation and tinnitus in mice with noise-induced hearing loss." (PMID 34020590, 2021). "Moreover, in mice, microglial ablation and TNF-alpha antagonism both decrease tinnitus signs, and TNF-alpha KO mice are resilient to noise trauma-induced tinnitus." (PMID 33329293, 2020). "The biomarkers related to tinnitus are peroxynitrite, nuclear factor kappa beta (NF-kB), and elevated intracellular calcium, with increased markers of proinflammatory activity such as cytokines, tumor necrosis factor-alpha (TNF-α), and interleukin-1 (IL-1)." (PMID 33383894, 2020).
Tinnitus (continued). "Therefore, it is possible that the tinnitus induced by cortical TNF-α infusion was weaker than that induced by noise exposure because of the lack of subcortical involvement." (PMID 31211773, 2019). "We had found that spirulina water extract, with its ant-inflammatory and anti-oxidative abilities, could reduce salicylate-induced tinnitus and up-regulation of TNF-alpha, IL-1beta, NR2B, and COX-2." (PMID 27590453, 2016). "Others have reported that salicylate can increase TNFα levels in models of tinnitus." (PMID 25874611, 2015). "Recently, our study group found that mRNA expression levels of the NR subtype 2B (NR2B) gene, tumor necrosis factor –α (TNF-α) and interleukine-1β (IL-1β) genes were elevated significantly in the cochlea and in the inferior colliculus (IC) in salicylate-induced tinnitus." (PMID 23533584, 2013). "We conclude that salicylate treatment resulting in tinnitus augments expression of the TNF-α and IL-1β genes in cochlea and IC of mice, and we suggest that these proinflammatory cytokines might lead to tinnitus directly or via modulating the NMDA receptor." (PMID 21477330, 2011). "Furthermore, CoQ10 possesses anti-inflammatory properties, which may help reduce inflammation by targeting pro-inflammatory cytokines like IL-6 and TNF-α, potentially contributing to the alleviation of tinnitus symptoms." (PMID 39850225, 2025). "Additionally, emerging evidence suggests that neuroinflammation may play a large role in the development of tinnitus and the influence of various proinflammatory cytokines such as TNF-α, IL-6, β-2GP1 and IL-1 has been described." (PMID 38327985, 2024). "Tumor necrosis factor-alpha (TNFα) may promote neuroinflammation prompting tinnitus." (PMID 36902722, 2023). "Furthermore, the pharmacological blockade of TNF-α reduced tinnitus." (PMID 37305742, 2023). "In animals, the increases in TNF-α were detected almost directly after tinnitus induction in most cases, while in humans, cytokine levels were measured in subjects with chronic tinnitus, i.e., the measurements took place much longer after the start of tinnitus." (PMID 35207270, 2022). "This proves that TNF-α is essential for the development of tinnitus, but not for hearing loss." (PMID 35207270, 2022). "However, TNF-α protein levels in the IC were significantly decreased in the Spirulina group (0.59±0.13 versus 1.51±0.19, p<0.001) and in the C-PC group (0.53±0.04 versus 1.51±0.19, p<0.001), compared with the tinnitus group." (PMID 23533584, 2013). "Therefore, it is also reasonable to hypothesize that TNF-α and IL-1β might contribute to tinnitus via augmenting NMDA receptor expression and/or its functions." (PMID 21477330, 2011). "Experimental studies found an increase of TNF-α in the cochlea, the CN, the IC, and the AC, as well as an increase of IL-1β in the cochlea, the IC, the MGB, and the AC of animals with tinnitus." (PMID 35207270, 2022). "SP downregulated TNF-α mRNA and protein expression in the cochlea and inferior colliculus of SAMP8 mice with salicylate-induced tinnitus." (PMID 28636628, 2017). "CPC and S. platensis water extract reduced salicylate-induced tinnitus and down-regulated mRNA and protein expression for NR2B, TNF-α, IL-1β, and COX-2 genes in the cochlea and IC of SAMP8 mice." (PMID 27590453, 2016). "Salicylate-mediated changes in NR2B expression, as well as inflammatory mediators including tumor necrosis factor α (TNFα), cyclooxygenase-2 (COX-2), and interleukin-1β (IL1β), were also found in mice with behaviorally confirmed tinnitus." (PMID 25870582, 2015).